SMYD2 (SET and MYND domain containing 2)
Diseases named in the same sentence as SMYD2 in open-access papers (continued):
Sharing a sentence is not in itself a finding about the gene and the disease.
atherosclerosis (1 paper, 2022). A disease characterized by the build-up of fatty material and calcium deposition in the arterial wall resulting in partial or complete occlusion of the arterial lumen. "Emerging evidence has revealed that vascular endothelial senescence is a strong predictor of mortality in diverse vascular aging-related diseases such as atherosclerosis, hypertension, and diabetes, thus we are curious whether Smyd2 is associated with these vascular aging-related diseases." (PMID 36585926, 2022). "We found a higher expression of Smyd2 in the aorta of atherosclerosis mice compared to that of control mice." (PMID 36585926, 2022).
cerebral infarction (1 paper, 2024). An ischemic condition of the brain, producing a persistent focal neurological deficit in the area of distribution of the cerebral arteries. "Conversely, in the Smyd-2 overexpression group, the cerebral infarction volume increased markedly, the neurobehavioral scores declined, and there was extensive neuronal damage and diffuse ferrous ion deposition in the hippocampus and cortex." (PMID 39682718, 2024). "The experimental results showed that Smyd-2 knockout could reduce the cerebral infarction volume, improve the neurologic deficit scores, alleviate neuronal demyelination, and reduce the number of degenerative neurons in the hippocampus after CIR." (PMID 39682718, 2024). "However, Smyd-2 overexpression significantly increased the volume of cerebral infarction, significantly decreased the neurologic deficit scores, aggravated neuronal demyelination and degeneration, and increased vacuole-like structures between neurons induced by CIR." (PMID 39682718, 2024). "In the Smyd-2 knockout group, we observed significant reductions in the cerebral infarction volume and histopathological damage, the absence of hippocampal ferrous ion deposition, and a notable improvement in neurobehavioral scores following CIR." (PMID 39682718, 2024).
cervical tumor (1 paper, 2019). "Interestingly, results showed that SMYD2 was mainly localized in the cytoplasm and highly expressed in cervical tumor tissues." (PMID 31548876, 2019).
chronic kidney disease (1 paper, 2025). Impairment of the renal function secondary to chronic kidney damage persisting for three or more months. "SMYD2 has been shown to act as an oncogene to promote disease progression in a variety of cancer diseases, but its role in chronic kidney diseases (CKD) pathogenesis has not been fully elucidated." (PMID 40391402, 2025).
colitis (1 paper, 2021). Inflammation of the colon. "We firstly used the Smyd2+/‐ mice to evaluate the roles of SMYD2 on colitis, collagen‐induced arthritis (CIA) and imiquimod induced psoriasis." (PMID 34841684, 2021). "The colon length in Smyd2+/− group was significantly longer than in the colitis WT mice." (PMID 34841684, 2021). "It has been testified that the Bay‐598 is a highly potent and selective inhibitor for SMYD2, the treating with 50 mg/kg Bay‐598 could substantially reduce the inflammation process in DSS‐induced colitis mice model and the psoriasis mice model." (PMID 34841684, 2021).
COVID-19 (1 paper, 2022). A disease caused by infection with severe acute respiratory syndrome coronavirus 2. "In addition, oral administration of BAY598 has been shown to reduce SMYD2 function in an esophageal ex vivo model, suggesting that BAY598 administration may have therapeutic potential in COVID-19 treatment." (PMID 35455942, 2022).
diabetes (1 paper, 2022). "For diabetes, the db/db mice and their control db/m mice were obtained and found the Smyd2 level was significantly enhanced in arteries of db/db mice compared with the db/m mice." (PMID 36585926, 2022).
emphysema (1 paper, 2023). "LLY-507-loaded PVA-IONPs significantly inhibited SMYD2 activity, reducing emphysema, congestion, hemorrhage, and tumor growth." (PMID 37513898, 2023). "The loss of SMYD2 due to LLY-507 suppressed tumor growth, emphysema, hemorrhage, and congestion considerably." (PMID 37513898, 2023).
endometrial carcinoma (1 paper, 2024). A malignant tumor arising from the epithelium that lines the cavity of the uterine body. "In endometrial carcinoma, the mutation frequencies were 3.3% for SMYD1, 2.1% for SMYD2, 2.1% for SMYD3, 2.1% for SMYD4, and 2.4% for SMYD5." (PMID 38892284, 2024).
endothelial dysfunction (1 paper, 2022). In vascular diseases, endothelial dysfunction is a systemic pathological state of the endothelium (the inner lining of blood vessels) and can be broadly defined as an imbalance between vasodilating and vasoconstricting substances produced by (or acting on) the endothelium. "Taken together, these results show that Smyd2 enhances Sphk and S1PR3 expression and negatively regulates S1PR1 expression, resulting in endothelial dysfunction." (PMID 35297562, 2022).
gastrointestinal stromal tumor (1 paper, 2022). "SMYD2, as an oncogene, has been involved in multiple types of cancer, but the potential role of SMYD2 in gastrointestinal stromal tumors (GIST) remains enigmatic and requires further investigation." (PMID 35668081, 2022).
gynecological cancers (1 paper, 2020). "Additionally, among gynecological cancers, we reported that the histone methyltransferase SMYD2 is overexpressed in HGSOC cells and that the suppression of SMYD2 with either small interfering RNA (siRNA) or its selective inhibitor results in reduced growth and increased apoptosis." (PMID 33339442, 2020).
Hepatic steatosis (1 paper, 2025). Steatosis is a term used to denote lipid accumulation within hepatocytes. "Through a strategy of in vivo lineage tracing, it was recently discovered that deletion of a protein methyltransferase SMYD2 has a protective role in hepatic steatosis." (PMID 40538802, 2025).
Hypertension (1 paper, 2022). The presence of chronic increased pressure in the systemic arterial system. "For hypertension, we constructed a two-kidney and one-clip renovascular hypertensive (2K1C) mice model and found the expression of Smyd2 increased accompanied by upregulation of the senescence markers (p21, VCAM-1, and IL-6)." (PMID 36585926, 2022).
ischemic disease (1 paper, 2024). Lack of blood supply to an area of the body, resulting in impairment of tissue oxygenation.
Kidney Cyst (1 paper, 2022). Abnormal fluid filled sac within the kidney, either acquired or congenital. "Given that both STAT3 and NF-κB are the substrate of SMYD2 in several tumor cells and kidney cyst epithelial cells, we suggest that methylation of STAT3 and NF-κB by SMYD2 may promote cisplatin-induced AKI." (PMID 36046818, 2022).
kidney damage (1 paper, 2022). "SMYD2 and trimethylated histone H3K36 (H3K36Me3) were highly expressed in the kidney following cisplatin treatment; administration of AZ505 remarkedly inhibited their expression, along with improving kidney function and ameliorating kidney damage." (PMID 36046818, 2022).
liver disease (1 paper, 2024). "Given that SMYD2 has also been linked to the development of metabolic‐associated steatotic liver disease, we predict that SMYD2 plays a role in regulating metabolic adaptations caused by sudden reductions in bioenergetic demand." (PMID 39609254, 2024).
metastatic tumors (1 paper, 2022). "Further comparison among normal, primary, and metastatic tumors showed the significant overexpression of SMYD2 in metastatic PC." (PMID 35884603, 2022).
nephrolithiasis (1 paper, 2024). The presence of a calculus in the pelvis of the kidney; this is most often composed of mineral salts and proteins. "Collectively, these results suggest that SMYD2 expression and glycolysis are upregulated in the cytoplasm of damaged RTCs in human kidney tissues with nephrolithiasis, indicating their association with renal injury and fibrosis." (PMID 39457592, 2024). "We analyzed human kidney specimens to investigate the relationship between SMYD2 and nephrolithiasis and the metabolism of kidney tissues with nephrolithiasis." (PMID 39457592, 2024). "To study the regulatory role of SMYD2 in glycolysis, we treated the glyoxylate-induced nephrolithiasis mice with a highly selective SMYD2 inhibitor, AZ505." (PMID 39457592, 2024). "The targeted inhibition of SMYD2 and glycolysis emerges as a promising treatment for CaOx crystal-induced renal injury and fibrosis, offering potential as an effective therapy to prevent kidney stone recurrence." (PMID 39457592, 2024). "Immunofluorescence analysis showed increased SMYD2 expression in human kidney specimens with nephrolithiasis compared to the control (CON) group, i.e., without nephrolithiasis." (PMID 39457592, 2024).
neuroblastoma (1 paper, 2021). Neuroblastoma (NB) is the most common solid, extracranial childhood tumor. "SMYD2 expression in neuroblastoma tumours was also predictive of patient outcome." (PMID 33968920, 2021).
Obesity (1 paper, 2022). Accumulation of substantial excess body fat. "Next, WT and Smyd2+/− mice were subjected to a 60% HFD for 12 weeks to investigate the effects of Smyd2 on HFD-induced obesity." (PMID 36270984, 2022). "Further studies are necessary to take advantage of adipose-specific Smyd2 knockout mice to elucidate the regulatory functions of Smyd2 in obesity in vivo." (PMID 36270984, 2022). "Our findings revealed that Smyd2 contributes to the process of adipocyte differentiation and inhibiting Smyd2 might represent a viable strategy for the therapy of obesity in humans." (PMID 36270984, 2022). "In vivo functional validation, Smyd2+/− mice exert significant fat loss but not susceptible to HFD-induced obesity." (PMID 36270984, 2022). "Inhibition of Smyd2 might represent a viable strategy for anti-adipogenesis and maybe further alleviate obesity-related diseases in humans." (PMID 36270984, 2022). "Besides, Smyd2+/− mice fed with normal diets exert significant fat loss but are not susceptible to HFD-induced obesity due to the heterozygous phenotype." (PMID 36270984, 2022). "Furthermore, Smyd2+/− mice exert significant fat loss but are not susceptible to HFD-induced obesity in vivo." (PMID 36270984, 2022). "However, the contribution of Smyd2 in adipogenesis and obesity remains unknown." (PMID 36270984, 2022). "However, the role of Smyd2 in metabolic diseases, such as obesity, has not been reported." (PMID 36270984, 2022). "Smyd2+/− mice may regulate only some of the adipogenesis marker genes in vivo, but not enough to alleviate HFD-induced obesity." (PMID 36270984, 2022).
occlusive vascular diseases (1 paper, 2023). "Hence, we conclude that SMYD2 is a novel regulator of VSMC contractile phenotype and intimal hyperplasia via a myocardin-dependent epigenetic regulatory mechanism and may be a potential therapeutic target for occlusive vascular diseases." (PMID 37090651, 2023).
osteoarthritis (1 paper, 2021). A noninflammatory degenerative joint disease occurring chiefly in older persons, characterized by degeneration of the articular cartilage, hypertrophy of bone at the margins and changes in the synovial membrane. "We examined SMYD2 expression in clinical synovium samples collected from RA and osteoarthritis (OA) patients and healthy donators." (PMID 34841684, 2021).
osteosarcoma (1 paper, 2024). A usually aggressive malignant bone-forming mesenchymal neoplasm, predominantly affecting adolescents and young adults. "We observed similar results in U2OS osteosarcoma cells indicating a general requirement of SMYD2 for CHMP2B proper localization at the ICB in different cell types undergoing cytokinesis." (PMID 38740816, 2024).
prostate adenocarcinoma (1 paper, 2022). "Findings showed that SMYD2 is overexpressed in many cancer types, including breast, lung, liver, and prostate adenocarcinoma." (PMID 35884603, 2022).
psoriasis (1 paper, 2021). An autoimmune condition characterized by red, well-delineated plaques with silvery scales that are usually on the extensor surfaces and scalp. "As the Histological assessment of back skin by H&E staining and the ELISA assay demonstrated that the Smyd2+/‐ mice showed powerful resistance to psoriasis." (PMID 34841684, 2021).
renal tumor (1 paper, 2019). "Increased expression of SMYD2 was initially identified in renal tumor tissue." (PMID 31866860, 2019). "While it has been shown that SMYD2 is also highly expressed in human kidney tumors, there is no report about SMYD2 expression in other human kidney diseases so far." (PMID 31866860, 2019).
retinoblastoma (1 paper, 2011). A malignant tumor that originates in the nuclear layer of the retina.
rheumatoid arthritis (1 paper, 2021). A chronic, systemic autoimmune disorder characterized by inflammation in the synovial membranes and articular surfaces. "SMYD2 was evaluated in synovial tissue and cells derived from rheumatoid arthritis patients." (PMID 34841684, 2021).
Stroke (1 paper, 2022). Sudden impairment of blood flow to a part of the brain due to occlusion or rupture of an artery to the brain. "Importantly, our findings demonstrate that stroke causes upregulation of Smyd2 in the brain." (PMID 35297562, 2022). "Our results suggest new avenues for the development of stroke therapeutics, through elucidating the processes of Smyd2‐mediated BBB disruption in perfusion injury." (PMID 35297562, 2022). "The present study provides previously unexplored evidence that endothelium‐derived Smyd2 mediates BBB disruption following stroke." (PMID 35297562, 2022). "Given the substantial deleterious consequences of BBB dysfunction during stroke, Smyd2 represents a novel opportunity for the therapeutic improvement of cerebrovascular integrity." (PMID 35297562, 2022). "In summary, Sphk/S1PR is involved in Smyd2‐mediated endothelial barrier disruption in stroke." (PMID 35297562, 2022). "Increased Smyd2 impairs S1PR1 formation and induces S1PR3 production, which is detrimental to TJs and BBB dysfunction after stroke." (PMID 35297562, 2022).
virus infection (1 paper, 2023). "Taken together, deficiency of Smyd2 promotes phosphorylation of IRF3 in macrophages in response to virus infection, which leads to increased translocation of dimerized IRF3 to the nucleus to promote IFN-I production." (PMID 37673879, 2023). "The Smyd2-deficient mice are more resistant to viral infection by producing more IFN-I and proinflammatory cytokines." (PMID 37673879, 2023). "Therefore, Smyd2-deficient mice have more potent resistance against viral infection by production of more IFN-I and proinflammatory cytokines." (PMID 37673879, 2023). "Our study identifies SMYD2 as a negative regulator of IFN-I production against virus infection." (PMID 37673879, 2023). "In addition to the inhibition of SMYD2 by viral infection, we also found that SMYD2 expression was decreased by stimulation of both RNA and DNA virus, which suggested the broad significance of SMYD2 in the inhibition of innate immune response." (PMID 37673879, 2023). "In addition, the viral infection-induced reduction of SMYD2 in the early stage of innate response may provide new insight into the effective activation of antiviral innate immune response by relieving the suppressor." (PMID 37673879, 2023). "Here we report that lysine methyltransferase SMYD2 inhibits the expressions of IFN-I and proinflammatory cytokines in macrophages upon viral infections." (PMID 37673879, 2023). "Mechanistically, SMYD2 inhibits IRF3 phosphorylation in macrophages in response to viral infection independent of its methyltransferase activity." (PMID 37673879, 2023). "Therefore, SMYD2 inhibits the production of IFN-I and proinflammatory cytokines IL-6 and TNF-α in immune cells upon viral infection." (PMID 37673879, 2023). "Therefore, we discovered the non-canonical function of SMYD2 in the inhibition of IFN-I production in macrophages in response to viral infection." (PMID 37673879, 2023).